OR13D1 (olfactory receptor family 13 subfamily D member 1)
Description:
Odorant receptor.
Synonyms: OR9-15
Gene: Protein-coding gene on chromosome 9 (104,694,518 to 104,695,462, forward strand). Ensembl gene ENSG00000179055.
Subcellular location: Cell membrane
Pathways (Reactome):
Sensory Perception: Expression and translocation of olfactory receptors
Genetic constraint (gnomAD): Loss-of-function variants: 0 observed, 0.36 expected, observed/expected ratio (o/e) 0, 90% interval 0 to 1.86. That is too few expected variants to judge how well the gene tolerates losing a copy. Missense variants: 353 observed, 385.43 expected, observed/expected ratio (o/e) 0.92, 90% interval 0.84 to 1. Synonymous variants: 125 observed, 142 expected, observed/expected ratio (o/e) 0.88, 90% interval 0.76 to 1.02.
Homologues: Orthologues: chimpanzee OR13D1 (98% identical), dog OR13D1B (87% identical), mouse Or13d1 (86% identical), rat Or13d1 (84% identical), guinea pig OR13D1 (82% identical), rabbit OR13D1 (78% identical). Paralogues in human: OR2K2 (61% identical), OR13C2 (60% identical), OR13C9 (60% identical), OR2S2 (59% identical), OR13C4 (59% identical), OR13C5 (59% identical), OR13C8 (59% identical), OR13C3 (57% identical), OR13J1 (50% identical), OR2D3 (48% identical), OR10A7 (48% identical), OR2B2 (48% identical), and 80 more.
Diseases named in the same sentence as OR13D1 in open-access papers:
OR13D1 is named in the same sentence as 2 diseases in open-access papers, as found by Europe PMC text mining. Sharing a sentence is not in itself a finding about the gene and the disease.
OR13D1 shares sentences with these, for which no sentence is quoted: neurodegenerative disease (1 paper); Parkinson disease (1).